ENSG00000258529 (novel protein)
Gene: Protein-coding gene on chromosome 11 (111,786,286 to 111,879,425, reverse strand). Ensembl gene ENSG00000258529.
Genetic constraint (gnomAD): Loss-of-function variants: 76 observed, 103.11 expected, observed/expected ratio (o/e) 0.74, 90% interval 0.61 to 0.89. Missense variants: 918 observed, 1,040 expected, observed/expected ratio (o/e) 0.88, 90% interval 0.83 to 0.93. Synonymous variants: 384 observed, 385.01 expected, observed/expected ratio (o/e) 1, 90% interval 0.92 to 1.09.